ITGAV (integrin subunit alpha V)
Description:
The alpha-V (ITGAV) integrins are receptors for vitronectin, cytotactin, fibronectin, fibrinogen, laminin, matrix metalloproteinase-2, osteopontin, osteomodulin, prothrombin, thrombospondin and vWF. They recognize the sequence R-G-D in a wide array of ligands. ITGAV:ITGB3 binds to fractalkine (CX3CL1) and may act as its coreceptor in CX3CR1-dependent fractalkine signaling. ITGAV:ITGB3 binds to NRG1 (via EGF domain) and this binding is essential for NRG1-ERBB signaling. ITGAV:ITGB3 binds to FGF1 and this binding is essential for FGF1 signaling. ITGAV:ITGB3 binds to FGF2 and this binding is essential for FGF2 signaling. ITGAV:ITGB3 binds to IGF1 and this binding is essential for IGF1 signaling. ITGAV:ITGB3 binds to IGF2 and this binding is essential for IGF2 signaling. ITGAV:ITGB3 binds to IL1B and this binding is essential for IL1B signaling. ITGAV:ITGB3 binds to PLA2G2A via a site (site 2) which is distinct from the classical ligand-binding site (site 1) and this induces integrin conformational changes and enhanced ligand binding to site 1. ITGAV:ITGB3 and ITGAV:ITGB6 act as receptors for fibrillin-1 (FBN1) and mediate R-G-D-dependent cell adhesion to FBN1. Integrin alpha-V/beta-6 or alpha-V/beta-8 (ITGAV:ITGB6 or ITGAV:ITGB8) mediates R-G-D-dependent release of transforming growth factor beta-1 (TGF-beta-1) from regulatory Latency-associated peptide (LAP), thereby playing a key role in TGF-beta-1 activation. ITGAV:ITGB3 acts as a receptor for CD40LG. ITGAV:ITGB3 acts as a receptor for IBSP and promotes cell adhesion and migration to IBSP. (Microbial infection) Integrin ITGAV:ITGB5 acts as a receptor for Adenovirus type C. (Microbial infection) Integrin ITGAV:ITGB5 and ITGAV:ITGB3 act as receptors for Coxsackievirus A9 and B1. (Microbial infection) Integrin ITGAV:ITGB3 acts as a receptor for Herpes virus 8/HHV-8. (Microbial infection) Integrin ITGAV:ITGB6 acts as a receptor for herpes simplex 1/HHV-1. (Microbial infection) Integrin ITGAV:ITGB3 acts as a receptor for Human parechovirus 1. (Microbial infection) Integrin ITGAV:ITGB3 acts as a receptor for West nile virus. (Microbial infection) In case of HIV-1 infection, the interaction with extracellular viral Tat protein seems to enhance angiogenesis in Kaposi's sarcoma lesions.
Synonyms: CD51; MSK8; VNRA; VTNR; IDNDC
Tractability: Small molecule: a structure with a bound ligand is known; a high-quality ligand is known; it has a high-quality binding pocket; it belongs to a druggable protein family. Antibody: an approved drug acts on it; its Gene Ontology location is reachable by antibodies, with high confidence; UniProt places it where antibodies can reach, with medium confidence; UniProt predicts a signal peptide or a membrane-spanning region. PROTAC: ubiquitination databases record sites on it; its protein half-life has been measured; a small molecule that binds it is known. Other modalities: a drug acting on it is in phase 2 or 3 trials.
Target class: Membrane receptor
Chemical probes: PD080807, PD084633, SB-223245
Gene: Protein-coding gene on chromosome 2 (186,590,010 to 186,680,901, forward strand). Ensembl gene ENSG00000138448.
Subcellular location: Cell membrane; Cell junction, focal adhesion
Subcellular location (Human Protein Atlas): Cytosol; Focal adhesion sites
Pathways (Reactome):
Extracellular matrix organization: ECM proteoglycans; Elastic fibre formation; Integrin cell surface interactions; Laminin interactions; Molecules associated with elastic fibres; Syndecan interactions
Cellular responses to stimuli: Mechanical load activates signaling by PIEZO1 and integrins in osteocytes; Turbulent (oscillatory, disturbed) flow shear stress activates signaling by PIEZO1 and integrins in endothelial cells
Immune System: Cross-presentation of particulate exogenous antigens (phagosomes); Neutrophil degranulation
Signal Transduction: TGF-beta receptor signaling activates SMADs; VEGFA-VEGFR2 Pathway
Developmental Biology: Signal transduction by L1
Hemostasis: PECAM1 interactions
Gene Ontology:
Molecular function: C-X3-C chemokine binding; coreceptor activity; extracellular matrix binding; extracellular matrix protein binding; fibroblast growth factor binding; fibronectin binding; insulin-like growth factor I binding; integrin binding; neuregulin binding; protease binding; protein binding; opsonin binding; protein kinase C binding; signaling receptor activity; transforming growth factor beta binding; signaling receptor binding
Biological process: angiogenesis; apolipoprotein A-I-mediated signaling pathway; apoptotic cell clearance; calcium ion transmembrane transport; cell adhesion; cell adhesion mediated by integrin; cell migration; cell-matrix adhesion; cell-substrate adhesion; endodermal cell differentiation; heterotypic cell-cell adhesion; integrin-mediated signaling pathway; negative chemotaxis; negative regulation of entry of bacterium into host cell; negative regulation of extrinsic apoptotic signaling pathway; negative regulation of lipid storage; negative regulation of lipid transport; negative regulation of lipoprotein metabolic process; negative regulation of low-density lipoprotein particle clearance; negative regulation of macrophage derived foam cell differentiation; positive regulation of cell adhesion; positive regulation of cell population proliferation; positive regulation of intracellular signal transduction; positive regulation of small GTPase mediated signal transduction; regulation of phagocytosis; and 14 more
Cellular component: alphav-beta3 integrin-HMGB1 complex; alphav-beta3 integrin-IGF-1-IGF1R complex; cell surface; extracellular exosome; filopodium membrane; focal adhesion; integrin alphav-beta1 complex; integrin alphav-beta3 complex; integrin alphav-beta5 complex; integrin alphav-beta6 complex; integrin alphav-beta8 complex; integrin complex; lamellipodium membrane; microvillus membrane; plasma membrane; ruffle membrane; alphav-beta3 integrin-PKCalpha complex; membrane; phagocytic vesicle; specific granule membrane; external side of plasma membrane
Genetic constraint (gnomAD): Loss-of-function variants: 46 observed, 72.89 expected, observed/expected ratio (o/e) 0.63, 90% interval 0.5 to 0.81. The upper end of that interval is the gene's LOEUF score, 0.81, which puts it in group 3 of 6, group 1 being the genes least tolerant of losing a copy. Missense variants: 736 observed, 846.12 expected, observed/expected ratio (o/e) 0.87, 90% interval 0.82 to 0.92. Synonymous variants: 315 observed, 312.05 expected, observed/expected ratio (o/e) 1.01, 90% interval 0.92 to 1.11.
Homologues: Orthologues: chimpanzee ITGAV (99% identical), macaque ITGAV (99% identical), pig ITGAV (95% identical), rabbit ITGAV (94% identical), dog ITGAV (93% identical), mouse Itgav (92% identical), rat Itgav (92% identical), guinea pig ITGAV (85% identical), tropical clawed frog itgav (70% identical), zebrafish itgav (59% identical), Caenorhabditis elegans pat-2 (28% identical), Drosophila melanogaster mew (26% identical), and 5 more. Paralogues in human: ITGA8 (47% identical), ITGA5 (46% identical), ITGA2B (37% identical), ITGA7 (28% identical), ITGA6 (27% identical), ITGA3 (25% identical), ITGA4 (23% identical), ITGA9 (23% identical), ITGAM (23% identical), ITGAX (22% identical), ITGA11 (22% identical), ITGA2 (22% identical), and 5 more.
Diseases named in the same sentence as ITGAV in open-access papers:
ITGAV is named in the same sentence as 165 diseases in open-access papers, as found by Europe PMC text mining. Sharing a sentence is not in itself a finding about the gene and the disease. The quoted sentences say what the papers report.
breast cancer (38 papers, 1998 to 2025). A primary or metastatic malignant neoplasm involving the breast. "Our data identify WASL, ITGAV and several additional cytoskeleton-associated molecules as novel invasion-promoting targets of miR-142-3p in breast cancer." (PMID 26657485, 2015). "ITGAV is implicated in tumor migration and invasion; thus, its overexpression has been reported in several epithelial tumors including gastrointestinal tract, prostate, and breast cancer." (PMID 33562532, 2021). "Overexpression of ITGAV is associated with poor relapse free survival of breast cancer patients." (PMID 32847144, 2020). "Integrin αvβ3 is implicated in facilitating metastasis of breast cancer cells to bone; decreased transcription of ITGAV after MUC1 siRNA may, therefore, suggest that MUC1 is involved in this lethal process as well." (PMID 16846534, 2006). "In addition, high expression of ITGAV significantly influenced the level of immune cell infiltration in lung adenocarcinoma and Triple-Negative breast cancer and was associated with poor prognosis in head and neck squamous cell carcinoma (HNSCC) and osteosarcoma." (PMID 40018050, 2025). "In recent years, ITGAV has been found to have significantly elevated expression in multiple tumors, such as prostate cancer, breast cancer, and osteosarcoma, and was considered to be a key component in various stages of tumor progression." (PMID 40018050, 2025). "It is reported that ITGAV silencing inhibits cell proliferation, invasion, and self-renewal of breast cancer cell lines by altering the expression of BCL2 and PXN (Cheuk, Siu, 2020)." (PMID 38374893, 2024). "It is reported that ITGAV silencing inhibits cell proliferation, invasion and self-renewal of breast cancer cell lines by altering the expression of BCL2 apoptosis regulator (BCL2) and paxillin (PXN)." (PMID 38374893, 2024). "Upregulated ITGAV expression has been identified in multiple cancers, such as gastric cancer cells, breast cancer, and hepatocellular carcinoma." (PMID 35927660, 2022). "In different human breast cancer cell lines, cell proliferation, invasion and renewal are restricted when ITGAV is inhibited." (PMID 35705916, 2022). "For breast cancer with high ITGAV expression, it has been recently suggested as a potential drug target." (PMID 33562532, 2021). "Previous studies have reported that ITGAV can regulate the proliferation, invasion, and metastasis of several cancers, such as gastric cancer, breast cancer, esophageal cancer, and colorectal cancer." (PMID 34195187, 2021). "Suppression of ITGAV inhibited cell growth, invasion, and self-renewal of breast cancer by altering BCL2 and PXN levels." (PMID 34249086, 2021). "We experimentally validated the predicted miR-142-3p targets ROCK2, CFL2, RAC1, WASL, and ITGAV in St-T1b cells using qPCR, which is in accordance with our previous findings in breast cancer cells." (PMID 32824678, 2020). "Silencing of ITGAV inhibited cell proliferation, invasion, and self-renewal of breast cancer cell lines by altering expression of BCL2 and PXN." (PMID 32847144, 2020). "Meanwhile, an ITGAV antagonist (cilengitide) was proven to inhibit angiogenesis and metastasis in breast cancer." (PMID 33302481, 2020). "SK2 KD universally downregulated expression of CAPZA1 (inhibition of autophagy and EMT) and also decreased expression of NSUN3, ADPGK and KLHDC10 in prostate and ITGAV in breast cancer cell lines." (PMID 30971929, 2019). "In MCF-7 breast cancer cells, knocking down ITGAV led to a significant inhibition of matrigel invasion." (PMID 30473751, 2018). "The integrin pair ITGAV:ITGB3 is expressed in breast cancer and can mediate metastasis to the bone." (PMID 39707454, 2024). "Thus, the higher colocalization of CD63 and ITGAV suggests a higher probability of ITGAV export into EVs in advanced breast cancer." (PMID 35923105, 2022).
breast cancer (continued). "For example, SVIL is intricately involved in tumour angiogenesis in liver cancer, whilst ITGAV silencing has proven to inhibit the cell proliferation and invasion of breast cancer cell lines and CDH5 has been demonstrated as a biomarker of metastatic breast cancer." (PMID 35682908, 2022). "Moreover, ITGAV promoted metastasis in several types of tumors such as breast cancer and prostate cancer." (PMID 26934001, 2016). "Indeed, drugs blocking ITGAV function have been successful in preclinical mouse models of breast cancer metastasis, underscoring the importance of miR-142-3p-dependent ITGAV regulation in our in vitro system." (PMID 26657485, 2015). "In contrast, we were not able to find a relationship between cilengitide sensitivity and cilengitide target integrins ITGAV, ITGB3, or ITGB5, contrary to previous observations in breast cancer cell lines and glioblastoma." (PMID 39707454, 2024). "Previous reports do however suggest coordinated transcriptional regulation of ITGAV and ITGB3 genes, including a recent study that demonstrates inhibition of ITGAV and ITGB3 transcription by Myc in a breast cancer model." (PMID 26918447, 2016). "MDA-MB-231 breast cancer cell lines express high levels of ITGA2 / ITGB1, ITGA3 / ITGB1, ITGA5 / ITGB1, ITGAV / ITGB3 integrins, compared to MCF-7, T47D, and ZR75-1 breast cancer cells." (PMID 25593998, 2014). "Furthermore, the ITGAV:ITGB3 integrin pair plays a role in cell survival following radiation therapy in both prostate cancer and breast cancer." (PMID 39707454, 2024). "To confirm if ITGAV could be released in tumour‐derived EVs, we analysed the colocalization of ITGAV and CD63 in tumours using a tissue array collected from 128 breast cancer patients at the Singapore National University Hospital." (PMID 35923105, 2022). "CD63, ITGB1, and ITGAV were abundant on the cell surface of breast cancer cells while CD11b was lacking." (PMID 35923105, 2022). "In breast cancer cells, either siRNA-depletion of WASL or miR-142-3p upregulation resulted in reduced formation of proinvasive membrane protrusions, whereas siRNA knockdown of either WASL or ITGAV, or miR-142-3p upregulation inhibited invasive growth in vitro." (PMID 32824678, 2020). "In summary, this study has revealed a novel role for miR-142-3p in regulating breast cancer cell invasiveness, which could at least partially be attributed to a targeting of WASL and ITGAV, and possibly additional cytoskeletal regulators." (PMID 26657485, 2015).
melanoma (28 papers, 2006 to 2025). A malignant, usually aggressive tumor composed of atypical, neoplastic melanocytes. "S100A4 and ITGAV displayed dataset-specific patterns: negatively associated with SC and CP in metastatic melanomas, but positively with MHC and EC in primary ones." (PMID 40943183, 2025). "For instance, inducing the expression of ITGAV in a melanoma cell line was found to be associated with increased metastatic potential." (PMID 38534932, 2024). "Those that effect a change in cell-cell cohesiveness (e.g. VIM, SPARC, COL4A1, and the integrins, ITGA4 and ITGAV), and have been shown to be over expressed in human or mouse melanoma samples, are each associated with one or more UV-miRNAs." (PMID 27149382, 2016). "For example, miR-146a exerts a paradoxical role in melanoma tumor cells: this miRNA inhibits tumor metastatic behaviors through ITGAV inhibition, while it concurrently favors tumor growth by activating the AKT/PTEN pathway." (PMID 34638272, 2021). "Insufficient cases were available to assess ITGAV transcripts as a biomarker in wildtype NRAS/BRAF melanoma." (PMID 30116025, 2018). "As a result, miR-146a is able to exert a paradoxical role in melanoma tumor cells: while it inhibits tumor metastasis through ITGAV inhibition, at the same time it favors tumor growth through the activation of the AKT/PTEN pathway." (PMID 29112174, 2017). "In line with this, two previous studies identified an up-regulation of integrin αV (ITGAV), one of the subunits of periostin receptor, as a predictive marker for melanoma metastasis in primary tumors." (PMID 18086302, 2007). "Inhibition of ITGAV also appears to increase T-cell killing of melanoma cells in vitro." (PMID 39639369, 2024). "Interestingly, Integrin-α V (ITGAV) is suppressed by miR-146a, a miRNA known to be involved in melanoma cell growth regulation and whose expression is upregulated during melanoma progression." (PMID 29112174, 2017). "While targeting αV integrins, including ITGAV, has shown promise in preclinical studies across various cancers, clinical trials in pancreatic cancer, head and neck cancer, lung cancer, melanoma, and glioblastoma using αV integrin inhibitors have been largely disappointing." (PMID 40739706, 2025). "As mentioned in this study, upregulation of fibronectin in turn modulates the transcription levels of integrin subunit alpha V (ITGAV) and integrin β1 (ITGB1), leading to an increased invasive power of melanoma cells." (PMID 35874839, 2022). "Secreted fibronectin regulates ITGAV (Integrin subunit alpha V) and ITGB1 (Integrin beta-1) expression, globally promoting melanoma cell adhesion and migration." (PMID 33800394, 2021). "Congruently, exploration of scRNA-seq data (via Single Cell Portal) revealed that elevated levels of ITGAV, ITGB3 and ITGB5 in myeloid cells are negative predictors of ICI therapy response in melanoma and renal cell carcinoma patients." (PMID 40281508, 2025).